YAP1 (Yes1 associated transcriptional regulator)
Diseases named in the same sentence as YAP1 in open-access papers (continued):
Sharing a sentence is not in itself a finding about the gene and the disease.
breast cancer (continued). "Recently, there were also reports in the literature that breast cancer dryness is promoted by miR-520b through the pathway Hippo/YAP, and miR-375 mediates Hippo/YAP pathway involvement in gastric carcinoma occurrence by hitting the YAP1/TEAD4-CTGF axis." (PMID 34167441, 2021). "The loss of RASSF1A or aberrations in the function of the Hippo-kinases LATS1 and 2 might shift the balance towards increased activation of YAP1, FOXM1 and ERα, fostering luminal breast cancer initiation and progression." (PMID 34831091, 2021). "Furthermore, nuclear YAP1 expression was a strong determinant of metastasis in TNBC (HR 2.384, 95%CIs 1.055–5.386, P = 0.0367), an aggressive subtype of breast cancer." (PMID 33718163, 2021). "BT474 cells, a hormone negative breast cancer cell line, were eventually selected for these assays due to their dependence on Yap1 co-transfection for reporter activity." (PMID 33504879, 2021). "lncRNA AATBC could promote breast cancer migration and invasion through binding with YBX1 to activate the YAP1/Hippo signaling pathway." (PMID 34244473, 2021). "Moreover, Nrg1/ErbB4 signaling can reduce the phosphorylation of YAP1 Ser127, and promote YAP1-dependent CTGF transcription through the production of the ErbB4–YAP1–TEAD complex in breast cancer cells." (PMID 32390875, 2020). "YAP1 was crucial for breast cancer cell proliferation, metastasis and drug resistance, the distinct functions of ERK1 and ERK2 on regulation of YAP1 suggested distinct roles of ERK1 and ERK2 on breast cancer progression." (PMID 31848326, 2019). "Silencing of ERK1 elevated YAP1 expression and TEAD activity in breast cancer cells." (PMID 31848326, 2019). "Herein we build on our original report by contrasting the functional, transcriptional, and pharmacological properties of the ESR1-e6>YAP1 fusion with additional ESR1 gene fusion events identified by RNA-seq of both early-stage and metastatic ER+ breast cancers." (PMID 30089255, 2018). "YAP1 interacts with various transcription factors, such as RUNX2, p73, p53BP2 and TEAD family members, that are essential for YAP1-mediated tumor growth and metastasis in melanoma and breast cancer." (PMID 27901498, 2017). "Importantly, RHAMM expression is also regulated at the transcriptional level by YAP1/TAZ and TEAD complex via binding at a specific site of the RHAMM promoter, consequently controlling cell migration and invasion in breast cancer cell lines." (PMID 29212185, 2017). "Negative regulation of YAP1 could explain the tumor suppressor functions of PTPN14, but in contrast, a recent publication showed that PTPN14 promotes aberrant cell growth in a breast cancer model." (PMID 27651363, 2016). "Moreover, in MDA-MB-231 mesenchymal breast cancer cells that lack E-cadherin junctions, expression of RASSF1C is sufficient to drive nuclear localization of β-catenin and YAP1." (PMID 26549256, 2015). "YAP1 overall protein intensity was scored as either absent, weak, intermediate or strong in two different primary breast cancer cohorts (screening cohort, n = 144 and randomised cohort, n = 500)." (PMID 24559095, 2014). "YAP1 protein intensity was scored as absent, weak, intermediate or strong in two primary breast cancer cohorts (n = 144 and n = 564) and mRNA expression of YAP1 was evaluated in a gene expression dataset (n = 1107)." (PMID 24559095, 2014). "To our knowledge, there are no reports concerning the expression of YAP1 and correlations with outcome in subsets of breast cancer patients, hence we set out to investigate and clarify the role of YAP1 in breast cancer." (PMID 24559095, 2014). "Altogether, these results suggest YAP1 to function as a treatment predictive factor in ER+ breast cancer, rather than a prognostic factor for the natural disease progression." (PMID 24559095, 2014).
breast cancer (continued). "METTL14 knockdown in MCF7 cells also resulted in the upregulation of YAP1, mirroring the response observed in TNBC, suggesting that the underlying molecular mechanism is consistent across various breast cancer subtypes, irrespective of the Hippo pathway activity." (PMID 39563370, 2024). "Interestingly, knockdown of lncRNA-FLG14107 dramatically downregulated YAP1 activation in breast cancer cells but not normal cells, thus, we renamed this lncRNA hippo pathway-related lncRNA (HPR)." (PMID 34462427, 2021). "Thus, mechanisms that lead to only a partial loss or altered functionality of the LATS proteins might be required to abrogate the RASSF1A-mediated suppression of YAP1, ERα and FOXM1, thereby fostering the initiation and progression of luminal breast cancer." (PMID 34831091, 2021). "These authors have shown that YAP1 and TEAD1 are involved in transcriptional control of the glucose transporter GLUT1, whereas knockdown of YAP1 inhibited glucose consumption, and lactate production of breast cancer cells, overexpression of GLUT1 restored glucose consumption and lactate production." (PMID 33427197, 2021). "To investigate whether LATS1 and/or LATS2 are indeed responsible for RASSF1A-mediated suppression of YAP1, ERα and FOXM1 expression in ERα+ breast cancer cells, we employed stable knockdown of either LATS1, LATS2 or LATS1+LATS2 in RASSF1A-conditional MCF7 cells." (PMID 34831091, 2021). "Finally, based on the upregulation of YAP1/TAZ expression after trastuzumab treatment, we investigated the clinical significance of YAP1/TAZ expression on acquired trastuzumab resistance in metastatic HER2-positive breast cancer patients." (PMID 32365528, 2020). "Given that dysregulation of the pathways controlled by YAP1 and TEAD family members exerts a significant impact on cancer development and therapeutic resistance, we decided to explore the impact of our findings in the generation of resistance to trastuzumab in human breast cancer." (PMID 32365528, 2020). "Additional studies are needed to determine the molecular mechanism on regulation of YAP1 mRNA levels by ERK1; however, our data firstly suggested that ERK1 expression might be used as biomarker for prediction the prognosis in patients with breast cancer." (PMID 31848326, 2019). "Interestingly, our RNA-seq analysis indicated that TAZ was not highly expressed in TICs from primary mammary tumors at both mRNA and protein levels, while Yap1 was specifically activated within these cells." (PMID 26695440, 2016). "Overexpression of YAP1 leads to oncogenic transformation of the immortalised MCF10A human breast cell line and the TEAD-interaction domain of a constitutively active YAP1S127A mutant has been shown to promote tumour growth and metastasis of murine mammary carcinoma cell lines." (PMID 24559095, 2014). "Consequently, the findings pertaining to the role of the piR-31115/METTL3/YAP1/IGF2BP2 signalling pathway in tumour angiogenesis may not be directly applicable to all TNBC cases or other breast cancer types." (PMID 39820521, 2025). "However, several other studies have suggested that survival is not significantly affected by YAP1 expression in breast cancer, or YAP1 may in fact act as a tumor suppressor." (PMID 33718163, 2021). "Overexpression of YAP1 also contributed to poor outcomes and drug resistance in non-SCLC (NSCLC), liver cancer, stomach cancer, breast cancer, and colorectal carcinoma, in addition to SCLC." (PMID 37752152, 2023). "In breast cancer stem cells, TAZ, not YAP1, has been shown to be a key regulator of breast cancer stem cells." (PMID 27911857, 2017). "The decision to test MAPK1/ERK2 only in the RT-PCR assays was based on reports that show MAPK3/ERK1 association with a better prognosis and its role in modulating the YAP1 signaling pathway, indicating that MAPK3 is a negative regulator of breast cancer development." (PMID 33707603, 2021).
breast cancer (continued). "YAP1/TEAD inhibitors may therefore have potential as a novel, non-chemotherapeutic treatment strategy when administered in combination with trastuzumab for HER2-positive breast cancer." (PMID 32365528, 2020).
colorectal cancer (152 papers, 2013 to 2026). A primary or metastatic malignant neoplasm that affects the colon or rectum. "Relationship between Yes‐associated protein 1 (YAP1) and deubiquitinating enzyme 3 expression and the clinical characteristics of colorectal cancer patients." (PMID 39968498, 2025). "For example, YAP-1 overexpression in colorectal cancer is associated with advanced pTNM stage, positive nodal status, tumor status, and cyclin D1 overexpression." (PMID 37476371, 2023). "In colorectal cancer patients, the oncogene YAP1 was significantly associated with an adverse prognosis and cetuximab resistanc." (PMID 37799806, 2023). "Yes-associated protein 1 (YAP1), a transcription factor of the Hippo pathway, comes up in the dependency screening of 20q amplified colorectal cancer cell lines, confirming a key role of the pathway in colorectal cancer." (PMID 34577783, 2021). "For example, METTL14 which suppresses colorectal cancer progression via regulating m6A-dependent miR-375/yes-associated protein 1 (YAP1) pathway, is downregulated in colorectal cancer tissues and cell lines." (PMID 32754191, 2020). "Growth arrest-specific transcript 5 (lncRNA GAS5) promotes Yes1-associated transcriptional regulator (YAP) degradation via the ubiquitin-proteasome pathway by interacting with the WW domain of the YAP protein in colorectal cancer." (PMID 32429086, 2020). "Gastric and colorectal cancers were the most frequently tumors reporting association of Hippo genes with patients’ prognosis; whereas the most represented gene was YAP1, reported as prognostic factor in 29 different studies in 14 cancer models." (PMID 30006603, 2018). "In colorectal cancer models driven by the loss of adenomatous polyposis coli gene, the up-regulation of gp130 expression leading to a heightened responsiveness to IL-6 and IL-11 also induces Yap1-dependent transcription." (PMID 37957015, 2024). "In colorectal cancer, the overexpression of HMGB1 and RAGE signaling may activate the transcription factor Yes-associated protein 1 (Yap1) through direct interaction with K-Ras, thereby promoting the proliferation and stemness of colorectal cancer cells." (PMID 38529373, 2024). "5-FU resistance is associated with YAP-1 overexpression in gastric and colorectal cancer." (PMID 37476371, 2023). "In a similar model for CRC, miR-375 could significantly reduce tumour growth in vivo and its pro-apoptotic role in colorectal cancer was associated with the targeting of YAP1." (PMID 34547721, 2021). "Studies also suggested that the signal path of HMGB1/RAGE could cause colorectal cancer to happen by activating the YAP1, and the higher levels of HMGB1 and RAGE could also give rise to glioma." (PMID 34369271, 2021). "The miR-195 was identified to suppress Hippo signaling by binding to the 3′-untranslated region (3′-UTR) of the human YAP1 mRNA, whose expression was validated in a separate cohort of colorectal carcinoma (CRC) and significantly associated with poor survival of patients." (PMID 34959397, 2021). "Deficiency of KDM3A may disrupt colorectal cancer cell growth and migration; however, these can be rescued by YAP1 overexpression." (PMID 32092824, 2020). "Yes-associated protein 1 (YAP1), as a direct downstream effector of the tumor suppressive hippo pathway, has been found to be elevated in various cancers, such as liver cancer, colorectal cancer, ovarian cancer, gastric cancer and non–small-cell lung cancer." (PMID 28915618, 2017). "Additionally, it was reported that Yap1 overexpression was associated with the lymph node metastasis, poor prognosis and progression of colorectal cancer, gastric carcinoma and ovarian cancer." (PMID 26695440, 2016). "Nuclear-YAP1 and FGF8 levels were plotted against each other, and the staining of nuclear YAP1 in high-FGF8-expressing tumors was stronger than that in low-FGF8-expressing tumors, suggesting that the expression of YAP1 is associated with FGF8 level in colorectal cancer." (PMID 25473897, 2015).
colorectal cancer (continued). "Finally, studies of prostate and colorectal cancers have demonstrated that miR-375 may participate in chemoresistance through interactions with Yes-associated protein 1 (YAP1) and Specificity Protein 1 (SP1) transcription factors." (PMID 36674758, 2023). "However, whether YAP1 is an oncogene in CRC (colorectal cancer) remains controversial, and the association between the subcellular localization of YAP1 and clinical implications in CRC remains unknown." (PMID 33240680, 2020). "Another study reported that SNTB1 promotes the malignant progression of colorectal cancer through the YAP1 and WNT/β-catenin pathways." (PMID 40774945, 2025). "Ras GTPase activating protein like 2 (RASAL2) promotes colorectal cancer through the LATS2/YAP1 axis of the Hippo signaling pathway." (PMID 40066231, 2025). "In colorectal cancer, YAP1 cooperates with DNMT3A to epigenetically silence tumor suppressors, facilitating metastasis." (PMID 40977060, 2025). "The long non-coding RNA (lncRNA) FTX elevates the levels of YAP1 by acting as a sponge for miR-215-3p, which in turn enhances aerobic glycolysis, cellular proliferation, migration, and invasion in colorectal cancer cells." (PMID 41311582, 2025). "Recent studies have established a strong correlation between elevated YAP1 activity and poor clinical outcomes in colorectal cancer (CRC) patients." (PMID 40872562, 2025). "With YAP1 activation, BIRC3/5 and MYC are the downstream targets of YAP1 under specific conditions, such as in cystic kidney epithelium and colorectal cancer cells." (PMID 38730465, 2024). "By marking m6A sites in flanking reverse complementary sequences, METTL3 induces circ1662 in colorectal cancer, which enhances colorectal cancer invasion and migration through YAP1 and SMAD3." (PMID 39550559, 2024). "Our findings highlight a regulatory network involving KLF15, LINC00689, PTBP1, LATS2, and the YAP1/β-catenin pathway in colorectal cancer, shedding light on potential therapeutic targets for colorectal cancer therapy." (PMID 38273088, 2024). "Previous studies suggested that as a tumor suppressor gene, DLG2 functioned by inhibiting stemness and promoting apoptosis in OC 27, and DLG2 suppressed colorectal cancer via enhancing phosphorylation of Yap1 in colorectal cancer." (PMID 37416779, 2023). "Some reports have measured the upregulation of YAP1 in tumors, such as gastric cancer, colorectal cancer, and pancreatic cancer." (PMID 37525215, 2023). "In colorectal cancer, M2 macrophage polarization was accelerated by YAP1, resulting in tumor formation." (PMID 37752152, 2023). "Numerous studies have demonstrated that YAP1 plays an important role in the development of colorectal cancer, promoting the proliferation and survival of colorectal cancer cells." (PMID 34974798, 2022). "METTL14 regulates the expression of miR-375 through DGCR8, and then inhibits the growth of cancer cells by targeting downstream YAP1 pathway, and also inhibits the invasion and migration of colorectal cancer cells." (PMID 35022030, 2022). "In general, these results demonstrate that MYL9 promotes the proliferation, migration and invasion of colorectal cancer cells through YAP1-Hippo signaling." (PMID 34974798, 2022). "Mechanically, MYL9 promoted the proliferation, invasion, migration and angiogenesis of colorectal cancer cells via YAP1-Hippo signaling." (PMID 34974798, 2022). "Overall, MYL9 promotes the proliferation, invasion, migration and angiogenesis of colorectal cancer cells by binding to YAP1 and thereby activating Hippo signaling." (PMID 34974798, 2022). "Our analysis of the TCGA database shows that YAP1 is highly expressed in esophageal cancer (P=0.498), gastric cancer (P=0.012), cholangiocarcinoma (P=0.018), pancreatic cancer (P=0.018), and colorectal cancer (P < 0.0001) relative to normal tissues." (PMID 35911146, 2022).
colorectal cancer (continued). "In our experiments, MYL9 was found to promote proliferation, invasion, migration, angiogenesis in colorectal cancer cells via binding to YAP1 and regulating Hippo signaling." (PMID 34974798, 2022). "Two studies reported dysregulation of YAP1 expression in colorectal cancer as a consequence of circPPP1R12A (hsa_circ_0000423) and circ0106714 binding with the target miRNA." (PMID 35673576, 2022). "As another example, circ1662, which directly binds to YAP1 to reduce its phosphorylation and promote its nuclear transfer, exhibited significantly higher expression in colorectal cancer tissues than in paired normal tissues." (PMID 35701841, 2022). "Afterward, YAP1 knockdown or the addition of Hippo antagonist inhibited the proliferation, invasion, migration and angiogenesis of colorectal cancer cells." (PMID 34974798, 2022). "For instance, YAP1 has been proved to be involved in tumorigenic properties of tumor cells in colorectal cancer, prostate cancer, and gastric cancer." (PMID 35601153, 2022). "Subsequently, YAP1 silencing or Hippo antagonist was performed to clarify the regulatory mechanisms of MYL9 in colorectal cancer progression." (PMID 34974798, 2022). "Yes1-associated transcriptional regulator (YAP1) was identified as an essential growth initiator or enhancers in several solid tumors, such as hepatocarcinoma, gastric cancer, and colorectal cancer." (PMID 35705994, 2022). "In the digestive system, MIR4435-2HG can up-regulate YWHAZ and YAP1 by competitively binding miR-22-3p and miR-206-3p to promote the progression of hepatocellular carcinoma and colorectal cancer, respectively." (PMID 35784328, 2022). "In colorectal cancer cells, by targeting YAP1 and SP1, miR-375-3p was found to repress tumorigenesis and partially modulate the chemoresistance of 5-fluorouracil." (PMID 35205628, 2022). "The expression of YAP1 was further examined by qPCR in pancreatic cancer, glioma, ovarian cancer, and colorectal cancer tissue samples and the corresponding normal tissue samples." (PMID 35685435, 2022). "Next, we analyzed mRNA levels of CIC, ETV4, and YAP1 in colorectal cancer (HT-29) and melanoma (A375) cells, expressing sgCtrl, sgCIC1, or sgCIC2." (PMID 36198276, 2022). "In conclusion, this study elucidated that MYL9 potentially regulated cell proliferation, migration, invasion and angiogenesis in colorectal cancer by interacting with YAP1 and regulating Hippo signaling." (PMID 34974798, 2022). "The results showed that the high expression of YAP1 was closely related to the poor OS of Asian population, colorectal cancer, gallbladder carcinoma, esophageal cancer, liver cancer, and pancreatic cancer." (PMID 35911146, 2022). "Conversely, hsa_circ_0106714 was also noted to alter YAP1 expression by sponging miR-942-5p, acting as a tumor suppressor in colorectal cancer." (PMID 35673576, 2022). "YAP1 was overexpressed in colorectal cancer, lymphoma, brain and CNS cancer, gastric and pancreatic cancer." (PMID 34257617, 2021). "Here, we demonstrate that oncogenic KRAS mutations upregulate the expression of selected amino acid transporters in colorectal cancer (CRC) cells through the hippo signaling effector YAP1." (PMID 34003553, 2021). "The YAP1/SIX2 axis is responsible for DDX3X-induced cell invasiveness in colorectal cancer harbouring wild-type KRAS." (PMID 33627125, 2021). "Cytoplasmic YAP1 has served as an important indicator for colorectal cancer and a dual cytoplasmic-nuclear pattern in prostate cancer, although it is frequently expressed in the nucleus in the cancer environment." (PMID 35201494, 2021). "The ceRNA network which is comprised by RP11-757G1.5/miR-139-5p/YAP1 is just the tip of an iceberg in colorectal cancer." (PMID 33023613, 2020). "The novel lncRNA EIF3J-AS1 was elucidated to aggravate cells proliferation and inhibit apoptosis in colorectal cancer via up-regulating YAP1 through sequestering miR-316." (PMID 32905397, 2020).